GALM (galactose mutarotase)
Description:
Mutarotase that catalyzes the interconversion of beta-D-galactose and alpha-D-galactose during galactose metabolism. Beta-D-galactose is metabolized in the liver into glucose 1-phosphate, the primary metabolic fuel, by the action of four enzymes that constitute the Leloir pathway: GALM, GALK1 (galactokinase), GALT (galactose-1-phosphate uridylyltransferase) and GALE (UDP-galactose-4'-epimerase). Involved in the maintenance of the equilibrium between the beta- and alpha-anomers of galactose, therefore ensuring a sufficient supply of the alpha-anomer for GALK1. Also active on D-glucose although shows a preference for galactose over glucose.
Synonyms: BLOCK25; GALAC4; GLAT; HEL-S-63p; IBD1
Tractability: PROTAC: ubiquitination databases record sites on it; its protein half-life has been measured.
Gene: Protein-coding gene on chromosome 2 (38,666,081 to 38,741,237, forward strand). Ensembl gene ENSG00000143891.
Subcellular location: Cytoplasm
Subcellular location (Human Protein Atlas): Nucleoplasm
Pathways (Reactome):
Disease: Defective GALM causes GALAC4
Metabolism: Galactose catabolism
Gene Ontology:
Molecular function: aldose 1-epimerase activity; protein homodimerization activity; carbohydrate binding; isomerase activity
Biological process: carbohydrate metabolic process; galactose catabolic process via UDP-galactose, Leloir pathway; galactose metabolic process; glucose metabolic process; hexose metabolic process
Cellular component: extracellular exosome; cytosol; cytoplasm
Genetic constraint (gnomAD): Loss-of-function variants: 35 observed, 32.66 expected, observed/expected ratio (o/e) 1.07, 90% interval 0.82 to 1.42. The upper end of that interval is the gene's LOEUF score, 1.42, which puts it in group 5 of 6, group 1 being the genes least tolerant of losing a copy. Missense variants: 375 observed, 366.63 expected, observed/expected ratio (o/e) 1.02, 90% interval 0.94 to 1.11. Synonymous variants: 172 observed, 156.18 expected, observed/expected ratio (o/e) 1.1, 90% interval 0.97 to 1.25.
Gene-disease validity (ClinGen):
ClinGen rates the evidence that GALM causes each of these diseases.
galactosemia 4 (autosomal recessive): Strong.
Homologues: Orthologues: chimpanzee GALM (99% identical), macaque GALM (98% identical), guinea pig GALM (90% identical), rabbit GALM (88% identical), dog GALM (87% identical), mouse Galm (85% identical), rat Galm (84% identical), tropical clawed frog galm (67% identical), zebrafish galm (59% identical), Drosophila melanogaster CG10467 (44% identical), Drosophila melanogaster CG32445 (40% identical), Drosophila melanogaster CG4988 (38% identical), and 3 more.
Diseases named in the same sentence as GALM in open-access papers:
GALM is named in the same sentence as 14 diseases in open-access papers, as found by Europe PMC text mining. Sharing a sentence is not in itself a finding about the gene and the disease. The quoted sentences say what the papers report.
galactosemia (12 papers, 2019 to 2025). "As all the GALM patients described in the first publication of GALM deficiency had abnormal NBS for galactosemia, we sought to compare our patient to previously reported patients." (PMID 40265446, 2025). "A new type of galactosemia was discovered, caused by a deficiency in galactose mutarotase (GALM), which catalyzes the epimerization between beta- and alpha-D-galactose." (PMID 40265446, 2025). "More recently, a fourth type of galactosemia was discovered, caused by a deficiency in galactose mutarotase (GALM), whose major role is the epimerization between beta- and alpha-D-galactose." (PMID 40265446, 2025). "Recently, pathogenic mutations in the galactose mutarotase (GALM) gene were identified in patients with unexplained galactosemia, giving rise to a new type of galactosemic." (PMID 36901862, 2023). "As concerns type IV galactosemia, this disease is caused by biallelic mutations in the GALM gene, leading to decreased activity of the GALM enzyme, which supports the equilibrium between the a- and b-anomers of D-galactose." (PMID 36615667, 2022). "We recently identified patients with galactosemia and biallelic variants in GALM, encoding galactose epimerase (GALM), an enzyme that is directly upstream of GALK1." (PMID 34842598, 2021). "Type IV galactosemia (OMIM#137030) is caused by mutations in the GALM gene causing deficiency in the galactose mutarotase enzyme (GALM; EC 5.1.3.3)." (PMID 33562227, 2021). "Although human GALM deficiency has not been described, we recently identified eight patients with galactosemia and biallelic variants in the GALM gene (MIM 137030)." (PMID 34842598, 2021). "In conclusion, here, we present a first case of GALM deficiency in the Netherlands, and highlight how different designs for galactosemia screening may lead to overlooking patients with GALM deficiency." (PMID 40265446, 2025). "GALM deficiency was subsequently designated as type IV galactosemia." (PMID 34842598, 2021). "Different designs of galactosemia screening may lead to overlooking patients with GALM deficiency." (PMID 40265446, 2025). "In addition, since several states and territories in the US have adopted the GALT mutation analysis as a second-tier test, it may be useful to expand the scope to other galactosemia-associated genes, including GALM, as another possible extension of neonatal screening for galactosemia." (PMID 34842598, 2021). "NBS systems for classic galactosemia often contain only GALT activity and Gal-1-P, thus patients with GALM deficiency will be missed." (PMID 34842598, 2021). "A novel type of genetic galactosemia, GALM deficiency, was reported in the NBS for classic galactosemia in Japan." (PMID 34842598, 2021). "Here, we report on a patient with GALM deficiency who had negative newborn screening for galactosemia in the Netherlands." (PMID 40265446, 2025). "At first, we were surprised that our GALM-deficient patient had a negative newborn screening for galactosemia." (PMID 40265446, 2025). "Other complications, such as those observed in classic galactosemia, have not been reported in GALM-deficient patients." (PMID 34842598, 2021). "Even in countries in which galactosemia is a screening target, the primary goal of NBS is to screen for classic galactosemia, which is the most severe type of galactosemia, and not GALM deficiency." (PMID 34842598, 2021). "Thus, several types of galactosemia can be distinguished: type I resulting from GALT deficiency, type II resulting from GALK deficiency, type III resulting from GALE deficiency, and type IV resulting from GALM deficiency, respectively." (PMID 36615667, 2022). "Galactosemia results in the deficiency of enzymes in the Leloir pathway including galactokinase (GALK1), galactose-1-phosphate uridylyltransferase (GALT), galactose mutarotase (GALM), or UDP-galactose 4′-epimerase (GALE), any of which can compromise the metabolism of galactose." (PMID 35118398, 2021).
galactosemia (continued). "Overall, most NBS systems for classic galactosemia in the US would not identify GALM deficiency." (PMID 34842598, 2021). "If more information on natural history and effect of diet in GALM deficiency becomes available and a lack of lactose-restricted diet indeed allows symptoms to arise, NBS design for screening galactosemia may be reconsidered." (PMID 40265446, 2025).
glioma (3 papers, 2021 to 2025). A benign or malignant brain and spinal cord tumor that arises from glial cells (astrocytes, oligodendrocytes, ependymal cells). "The GALM-encoded glucose-1-phosphate translocase plays a key role in glucose metabolism and drives glioma cell proliferation and tumor progression by promoting alterations in glucose metabolic pathways." (PMID 40299448, 2025). "Due to the remarkable clinical significance of GALM in glioma, we intended to further confirm the expression of GALM by Western blot and qRT-PCR in clinical specimens." (PMID 35127693, 2021). "By analyzing the expression levels of DUBs and their correlation with GALM in gliomas, combined with in vitro experiments, four DUBs were selected, namely, USP18, TNFAIP3, USP39, and USP38." (PMID 35127693, 2021). "Since protein GALM was rarely studied in glioma, we detected high expression of GALM by western blot and immunohistochemistry in glioma tissues." (PMID 35127693, 2021). "Then we further verified the expression of GALM by western blot, qRT-PCR, and IHC in glioma samples." (PMID 35127693, 2021). "Through the retrospective investigation of the six GMGs in the model, it was found that little has been known about GALM in glioma." (PMID 35127693, 2021). "And compared to that in IDH mutant gliomas, we found that GALM’s expression in IDH wild-type gliomas was overexpressed." (PMID 35127693, 2021). "Bioinformatic analyses revealed that the poor prognosis happened in glioma patients with high expression of GALM and that the expression of GALM was also related to the malignancy of gliomas." (PMID 35127693, 2021). "Notably, the expression of GALM increased significantly after overexpression of TNFAIP3 in the glioma cell." (PMID 35127693, 2021). "We found that GALM was overexpressed in glioma and could promote the epithelial-to-mesenchymal transition (EMT) process of glioma cells." (PMID 35127693, 2021). "And experiments in vitro showed that GALM could promote the epithelial-to-mesenchymal transition (EMT) process of glioma cells and could be regulated by TNFAIP3 in glioma cells." (PMID 35127693, 2021). "Since little is known about GALM in glioma, we focused our study on GALM." (PMID 35127693, 2021). "A higher expression level of GALM was observed in gliomas compared to normal brain tissues." (PMID 35127693, 2021). "Then, we explored the mechanism for the overexpression of GALM in glioma." (PMID 35127693, 2021). "Furthermore, we demonstrated that GALM was significantly related to the malignancy of glioma and could promote glioma cells’ EMT process." (PMID 35127693, 2021). "Furthermore, we proved that the expression of GALM was overexpressed in gliomas and that GALM could promote the EMT process of glioma cells." (PMID 35127693, 2021). "Therefore, we proposed that highly expressed GALM maintained by TNFAIP3 could promote the malignancy of glioma by regulating the EMT process." (PMID 35127693, 2021). "Furthermore, we demonstrated that knocking down the expression of GALM could affect the EMT process of glioma." (PMID 35127693, 2021). "Inspired by this, a glucose metabolism‐related gene (GMG)‐based model, including LDHA, GUSB, GLB1, GALM, and FBP1, was proposed based on protein‒protein interaction analysis to predict the prognosis of patients with glioma." (PMID 39830021, 2025). "After knocking down GALM with siRNA, we observed that the EMT process of glioma cells was significantly inhibited." (PMID 35127693, 2021). "GALM was significantly overexpressed in high-grade and IDH wild-type gliomas, which supported data analysis results." (PMID 35127693, 2021). "On account of the lack of research on protein GALM in gliomas, we intended to explore the function of GALM in glioma further." (PMID 35127693, 2021). "In conclusion, GALM was overexpressed in glioma and could promote the EMT process of glioma cells." (PMID 35127693, 2021). "A similar high expression of GALM was also found in 1p/19q non-codeletion gliomas." (PMID 35127693, 2021).
glioma (continued). "Furthermore, we demonstrated that GALM could promote the EMT process of glioma cells and was significantly related to the malignant degree of glioma." (PMID 35127693, 2021).
cataract (2 papers, 2021). Partial or complete opacity of the crystalline lens of one or both eyes that decreases visual acuity and eventually results in blindness. "This study highlights the importance of evaluating the whole galactose metabolism in terms of GALM deficiency in patients with cataracts." (PMID 35028268, 2021). "We are presenting two siblings with GALM deficiency; one patient presented with cataracts and her brother was asymptomatic." (PMID 35028268, 2021). "Further studies are needed to clarify the natural history of GALM deficiency in humans, including the full spectrum of cataracts and other phenotypes." (PMID 34842598, 2021). "Therefore, in NBS-negative babies without cataracts, the presence of GALM deficiency would not be noticed even if they had elevated blood galactose levels." (PMID 34842598, 2021).
alcohol abusers (1 paper, 2016). "The present study explored the relationship between SLC6A4, TPH2, and GALM genes and neurocognitive impairment in HIV-infected alcohol abusers." (PMID 27069689, 2016).
COVID-19 (1 paper, 2023). A disease caused by infection with severe acute respiratory syndrome coronavirus 2. "Clustering and shared upregulation of glycolytic enzyme encoding genes GALM, GAPDH, GPI, and ALDOA together with HIF1A, and transcripts regulating exhaustion (TIGIT and LAG3) suggested that hypoxia/anaerobic axis is associated with impaired CD8+TM function in COVID-19 BALF." (PMID 37029220, 2023).
developmental delay (1 paper, 2025). "The ANKS1B variant is thought to be the cause of her developmental delay, although we cannot completely rule out any effects of GALM deficiency on her development." (PMID 40265446, 2025). "We present the first patient with GALM deficiency who had negative NBS in the Netherlands and was identified at age 1.5 years during broad metabolic screening because of her global developmental delay, nystagmus, and a history of jaundice." (PMID 40265446, 2025).
giardiasis (1 paper, 2023). An infection of the small intestine caused by the flagellated protozoan giardia lamblia. "On the other hand, galactose mutarotase, aminomethyl transferase, and methylmalonyl-CoA epimerase expression were similar during giardiasis and UPEC infection." (PMID 36675151, 2023).
tumor (3 papers, 2018 to 2025). "The protein expression of CD44, HK3, KIF20A, and IDUA was higher in the tumor tissues compared to the normal tissue, and the protein expression of GALM and TGFA was lower in tumor tissues than normal, which was consistent with our results in TCGA." (PMID 33816274, 2021).
cancer (2 papers, 2023 to 2024). A tumor composed of atypical neoplastic, often pleomorphic cells that invade other tissues. "Interestingly, we found that four of the 28 prognostic RESs were associated with higher stemness in corresponding cancers, including RESs of GALM and IFI6 in LGG." (PMID 36969056, 2023). "For example, editing sites for GALM or IFI6 that led to higher expression were linked to lower survival and more cancer stemness." (PMID 36969056, 2023). "For instance, genes like SLC24A3, GALM, MPO, and ATP1B1 appear to be commonly down-regulated across various solid cancers, while other MRGs are frequently up-regulated in many cancer types." (PMID 38995414, 2024). "For example, GALM (or IFI6) editing sites associated with worse outcomes of LGG patients resulted in higher expression of GALM (or IFI6), and were correlated with higher cancer stemness." (PMID 36969056, 2023).
metabolic disease (1 paper, 2021). A congenital disorder (due to inherited enzyme abnormality) or acquired (due to failure of a metabolically important organ) disorder resulting from an abnormal metabolic process. "Galactose mutarotase (GALM) deficiency is an inherited metabolic disease caused by the deficiency of the first enzyme in the Leloir pathway." (PMID 35028268, 2021).
GALM also shares sentences with these, for which no sentence is quoted: infection (2 papers); mucopolysaccharidoses (1); Nystagmus (1); peroxisomal disorders (1).